ENSG00000221639
Synonyms: LOC124900180
Gene: Small nucleolar RNA gene on chromosome 4 (73,263,960 to 73,264,084, forward strand). Ensembl gene ENSG00000221639.
Gene Ontology:
Biological process: RNA processing
Cellular component: nucleolus
Homologues: Paralogues in human: SNORA3B (82% identical), SNORA3C (72% identical), SNORA3A (62% identical).